ERG (ETS transcription factor ERG)
Diseases named in the same sentence as ERG in open-access papers (continued):
Sharing a sentence is not in itself a finding about the gene and the disease.
cancer (continued). "PCA3 and TMPRSS2:ERG had additional independent predictive value for the prediction of PCa detection and progression, although PCA3 was limited in predicting aggressive cancer." (PMID 26339615, 2015). "This analysis, which was limited to the subset of ERG-positive and PTEN-deleted cancers where SOX9 had strongest prognostic impact in univariate analysis, revealed that the prognostic value of SOX9 was not independent from the established prognosticators." (PMID 26030748, 2015). "It has been suggested that urinary PCA3 and TMPRSS2:ERG fusion tests and serum PHI correlate to cancer aggressiveness-related pathological criteria at prostatectomy." (PMID 25079439, 2014). "The large number of tumors analyzed in this study enabled us to separately analyze cancer subgroups defined by molecular features, the most common of which is the TMPRSS2:ERG gene fusion." (PMID 24261794, 2013). "In summary, we evaluated both primary cancer patients and Met/CRPC patients for the presence of TMPRSS2/ERG rearrangements, AR gene copy number gain, and PTEN deletion using a three-marker FISH panel." (PMID 24098661, 2013). "Selected targets were confirmed by immunohistochemistry: NPY and PLA2G7 (up-regulated in ERG+ cancers), and AZGP1 and TFF3 (down-regulated in ERG+ cancers)." (PMID 23390522, 2013). "Among the 34 primary cancer patients with data available from all three markers, 6 of the 8 individuals with PTEN deletion (75%) also showed an abnormal TMPRSS2/ERG FISH result." (PMID 24098661, 2013). "The multiclass procedure identified two genes that were differentially methylated across all three carcinoma types at the 1% FDR level: THBS2 (FDR < 0.1%) and ERG (FDR < 0.1%)." (PMID 24175302, 2013). "P08-027N (age 54), in contrast, displayed a cancer-like signature: AGR2 = 0.61 (61 counts), AMACR = 2.33, CRISP = 11.21, ERG = 0.76, HPN = 0.34, PCA3 = 0.53 (data entries in magenta), compared to the non-cancer signature of P08-022N." (PMID 23029164, 2012). "Distinct alterations of the transcription factor ERG, an ETS-related gene, are observed in a variety of cancers." (PMID 22140532, 2011). "Despite the disagreement concerning the role of TMPRSS2/ERG in cancer initiation, cell invasion was suggested to be a consequence of TMPRSS2/ERG fusion both in vitro and in vivo." (PMID 21747944, 2011). "The ERG gene belongs to the ETS family of transcription factors and has been found to be involved in atypical chromosomal rearrangements in several cancers." (PMID 22140532, 2011). "Other candidates included DDC, MANEA, ZWINT, while ERG and SERPINA3 were examples of genes scored with decreased expression in LNCaP compared to CD26+ cancer." (PMID 20021671, 2009). "Among ERG negative cancers, Ki67LI was 1.7 ± 0.1 in 584 tumors with 1+, 2.7 ± 0.1 in 1,103 tumors with 2+, and 3.3 ± 0.1 in 747 tumors with 3+ MTAP staining (p < 0.0001)." (PMID 40554389, 2025). "MTAP expression provided significant prognostic value beyond the established parameters in all of the described scenarios in the subgroup of ERG negative cancers but not in ERG positive cancers." (PMID 40554389, 2025). "MTAP staining was significantly stronger in cancers harboring the TMPRSS2:ERG fusion than in ERG fusion negative tumors (p < 0.0001)." (PMID 40554389, 2025). "In both ERG negative and ERG positive cancers, four different multivariate analyses were performed to evaluate the clinical relevance of MTAP expression in different scenarios." (PMID 40554389, 2025). "It is therefore not uncommon that the prognostic impact of molecular factors varies between ERG positive, and ERG negative cancers." (PMID 40554389, 2025). "The ERG oncogene makes part of the TMPRSS2-ERG fusion, typically found in most PCa cancers." (PMID 40649790, 2025). "There was a strong positive association between AR expression and MTAP expression in all cancers as well as in subsets of ERG negative and ERG positive cancers (p < 0.0001 each)." (PMID 40554389, 2025).
cancer (continued). "By contrast, ERG+ cells did not expand in mice with luminal-restricted ERG expression (EP; K8-CreERT2) or generate invasive cancer after 9–12 months despite early and sustained luminal-specific ERG induction throughout the entire observation period." (PMID 40858905, 2025). "For example, 2+ to 3+ MTAP staining was seen in 78 % of ERG IHC negative, but in 92.8 % of ERG IHC positive cancers." (PMID 40554389, 2025). "In ERG negative cancers, high MTAP expression was related to deletions of PTEN (p < 0.0001), 8p21 (p < 0.0001), 5q21 (p = 0.0049), 12p13 (p = 0.0274), and 17p13 (p = 0.001)." (PMID 40554389, 2025). "High MTAP expression levels were strongly related to a high Ki67LI in 2,442 ERG negative but not in 2,229 ERG positive cancers." (PMID 40554389, 2025). "Considering the strong difference in MTAP expression between ERG positive and ERG negative cancers, these subgroups were separately analyzed for the role of MTAP expression." (PMID 40554389, 2025). "Upregulation of ETS TFs (primarily ERG) and downregulation of PAX2 are observed in approximately 20% of PIN and approximately 80% of EIN lesions, respectively, and facilitate transition to carcinoma." (PMID 40829174, 2025). "In ERG negative carcinomas, the levels of MTAP expression increased markedly with advanced pT stage and classical or quantitative Gleason grade (p < 0.0001 each), and high (3+) MTAP expression was strongly linked to early PSA recurrence (p < 0.0001)." (PMID 40554389, 2025). "This is consistent with the observation that ERG-positive tumors, unlike most other cancers, exhibit a more differentiated, less-plastic phenotype." (PMID 39347576, 2024). "Similarly, the suppression of miR-449a in ERG-positive PCa elevates SIRT1 expression, creating a feedback loop involving ERG, miR-449a, and SIRT1, which drives invasive cancer phenotypes." (PMID 39796040, 2024). "As reported in cancer and stem cells, “hockey stick” plots showed that H3K27ac signals were asymmetrically distributed across the genome, with disproportionately higher density at super-enhancers of T-ALL genes like MYC, TCF, ERG, and ETV640." (PMID 38352301, 2024). "A low level of PSAP expression was linked to PSA recurrence independent of pre- and postoperative prognostic markers in ERG-negative cancers." (PMID 37892063, 2023). "This genomic event results in the fusion of the ERG proto-oncogene with the androgen-driven promoter of the TMPRSS2, setting the transcription of the former under hormonal affection and resulting in its over-expression in cancer cells." (PMID 37185705, 2023). "Several genetically engineered mouse (GEM) models that overexpress ERG or ETV1 showed either minimal or no phenotype early time points, thus failing to recapitulate the cancer initiating ability of ETS translocation implicated by human genetics." (PMID 37018402, 2023). "On the contrary, PTEN alterations, as a primary lesion in cancer, did not display an increased risk for developing TMPRSS2: ERG fusions." (PMID 37185705, 2023). "In ERG-negative cancers, low PSAP proved to be an independent predictor of poor prognosis in scenarios 2, 3, and 4, while PSAP measurement did not provide independent prognostic information in ERG-positive cancers." (PMID 37892063, 2023). "In these cases, the N-terminal portion of TMPRSS2, including the cytosolic tail but not the catalytic domain, is commonly fused to the ERG transcription factor in cancer patients." (PMID 37896901, 2023). "Whereas the overexpression of ERG alone does not constitute a determinant for disease progression or overall survival, it could indicate the initiating trigger for the gene fusion upon other cancer cell regulatory pathways, such as a loss of PTEN, and thus reflect disease aggressiveness." (PMID 37185705, 2023).
cancer (continued). "Fusion-negative cancers (n = 50) were selected by sorting ERG expression level in descending order and selecting the bottom to 50th sample." (PMID 36579559, 2022). "Even though some published studies have validated that overexpressed TMPRSS2-ERG or ERG could promote cancer invasion ability and/or drug resistance, most reports on TMPRSS2-ERG are on the e1e4 form." (PMID 36088396, 2022). "In cancer, the abnormal expression of oncogenic transcription factors (e.g., FLI-1 and ERG) as well as negative regulators of carcinogenesis (e.g., FEV) in the ETS family induces the upregulation of genes that are known to promote cancer and the downregulation of genes that subdue cancer." (PMID 35548776, 2022). "Three genes (RUNX2, ERG and MMP3) are involved in “transcriptional misregulation in cancer”." (PMID 34830910, 2021). "In Black patients, the opposite pattern was observed; the percentage of any TMA spot positive for GSTP1 expressing cancer was higher in men who were ERG positive than ERG negative." (PMID 34191807, 2021). "While this signature was correlated with worse patient outcomes in breast and other independent cancer datasets, including PCa, the signature unsurprisingly fails to capture key characteristics of PCa such as ERG-rearrangement." (PMID 34311724, 2021). "As the 5q21 (CHD1) deletion is mainly occurring in ERG fusion‐negative cancers, we next analyzed PSA recurrence in the subsets of 5q21‐normal (n = 5835) vs. 5q21‐deleted (n = 658) patients." (PMID 33533127, 2021). "We performed the immunohistochemical evaluation of ERG status and its associations with clinico-pathological variables and neural parameters finding that ND PGP 9.5 was significantly higher in ERG-positive cancers compared to ERG-negative ones." (PMID 34277455, 2021). "Thus, we identify a bioactive ERG O'PROTAC that can degrade ERG protein and inhibit cancer cell growth in vitro." (PMID 34397171, 2021). "The association of high JUP protein expression and biochemical recurrence was mainly driven by the subset of TMPRSS2:ERG fusion‐negative cancers (P = 0.0003) and not seen in the ERG fusion‐positive subset (P = 0.258)." (PMID 33533127, 2021). "In contrast, the percentage of patients with ERG negative cancers that were GSTP1 positive was more similar in Black (12.9%) and White (9.4%) patients (P = 0.38)." (PMID 34191807, 2021). "Enrichment analysis was performed using HUGO symbols of genes recurrently hit per dataset, indicating that the pathway “Transcriptional misregulation in cancer [KEGG:05202]” was significantly more frequently hit (P = 1.6 × 10−4) within PCa due to TMPRSS2, ERG, ETV1, H3FA3, SLC45A3, and ELK4." (PMID 34891161, 2021). "The results of this analysis show that an independent prognostic role of TFAP2D measurement was limited to the pre-surgical scenario 4 in all cancers and ERG negative cancers (p = 0.0007 each)." (PMID 32143573, 2020). "These analyses identified ESRP1 expression, ESRP2 expression as well as our ESRP1/ESRP2 score as independent prognostic parameters in all cancers as well as the subset of ERG-negative and ERG-positive cancers in all four scenarios (p ≤ 0.05)." (PMID 33339518, 2020). "In a multivariate analysis including various postoperative and prognostic clinico-pathological features, SFRP4 protein expression emerged as an independent prognostic parameter in ERG negative cancers." (PMID 32677026, 2020). "Multivariable analyses were performed in all cancers and the subset of ERG‐negative and ERG‐positive cancers evaluating the clinical relevance of CTCF expression in different scenarios." (PMID 31736271, 2020). "Particularly, high CTCF expression was significantly associated with the presence of the transmembrane protease, serine 2:ETS‐related gene fusion: Only 10% of ERG‐negative cancers, but 30% of ERG‐positive cancers had high‐level CTCF expression (P < 0.0001)." (PMID 31736271, 2020).
cancer (continued). "PNUTS staining was significantly more prevalent in cancers harboring TMPRSS2:ERG rearrangements than in cancer lacking ERG fusions." (PMID 32377272, 2020). "That ERG expression is induced by ERK MAP Kinase pathway might, thus, explain the predominance of the CD138 expression in ERG positive cancers." (PMID 33195694, 2020). "The increased frequency of TFAP2D positive cancers in ERG positive (90%) compared to ERG negative subsets (74%) suggests an interaction between ERG and TFAP2D, either directly or via modulation of shared common downstream targets." (PMID 32143573, 2020). "This analysis revealed that the observed associations were largely caused by the subset of ERG negative cancers, while TFAP2D staining was unrelated to the analyzed features in ERG positive cancers." (PMID 32143573, 2020). "Subset analyses of ERG positive and ERG negative cancers revealed that the prognostic impact of TFAP2D expression was driven by the ERG-negative group (p < 0.0001)." (PMID 32143573, 2020). "These rates dropped to 8.3% in all and 5.9% in ERG negative cancers without 12q24 deletion (p < 0.0001 each)." (PMID 32677026, 2020). "In earlier studies, we had found several prognostic markers that were applicable solely to ERG-negative or ERG-positive cancers." (PMID 32417965, 2020). "In addition, AQP5 was the ERG that affected EC patients’ OS, PFS, and DFS, and we further explored its role in other cancer types through pan-cancer analysis." (PMID 33343628, 2020). "Our data suggest that loss of survivin is ERG dependent as survivin protein levels were clearly lower in ERG‐positive than in ERG‐negative cancers." (PMID 31893572, 2020). "Both, membranous and cytoplasmic CD138 immunopositivity, were more than 2 times more frequent in ERG positive than in ERG negative cancers (p < 0.0001)." (PMID 33195694, 2020). "SFRP4 positivity was markedly more frequent in ERG positive (77.4%) than in ERG negative cancers (57.4% p < 0.0001)." (PMID 32677026, 2020). "The similar prognostic role of ESRP overexpression in ERG-positive and ERG-negative cancers is a distinct advantage for using these proteins in routine diagnostics." (PMID 33339518, 2020). "The numbers of ERG-positive endothelial cells in cancer tissue were more than those in adjacent non-cancer tissue." (PMID 32591615, 2020). "PancRNA_Ets-1 facilitates the physical interaction between the RNA binding protein NONO and the transcriptional factor ERG, resulting in transactivation of ERG and increased cancer-related gene transcription." (PMID 32183847, 2020). "This also applied to the subset of ERG‐negative and ERG‐positive cancers (P < .0001 each) as well as in cancers without (P < .0001) and with PTEN deletion (P = .0013)." (PMID 31893572, 2020). "All these analyses revealed similar results to the entire patient cohort for both ERG positive and ERG negative cancers." (PMID 33195694, 2020). "In ERG-negative cancers, a statistically significant difference was also seen for 8 of 11 analyzed deletions." (PMID 32377272, 2020). "The analysis revealed for membranous CD138 staining significant associations with 10 deletions in all cancers, 4 deletions in ERG positive cancers, and 4 deletions in ERG negative cancers." (PMID 33195694, 2020). "(d–f): Impact of nuclear staining (irrespective of cytoplasmic staining) on PSA recurrence-free survival in (d) all cancers, (e) ERG negative cancers and (f) ERG positive cancers." (PMID 32488048, 2020). "The numbers of ERG positive endothelial cells in highly vascular cancer tissues were upregulated when compared to those in non-cancer tissues." (PMID 32591615, 2020). "High hnRNPA1 expression proved to be an independent prognostic parameter in all scenarios, however, limited to the subset of ERG-negative cancers." (PMID 32417965, 2020). "For both nuclear and cytoplasmic staining, these analyses revealed that YAP1 staining is linked to deletions of 8p and PTEN (10q) in both ERG positive and ERG negative cancers (p ≤ 0.0004 each)." (PMID 32488048, 2020).
cancer (continued). "SFRP4 belongs to the few biomarkers, which were found to be prognostic in either ERG positive or ERG negative cancers but not in both groups." (PMID 32677026, 2020). "As YAP1 was strongly associated with a positive ERG status, it is not surprising that YAP1 was either positively or inversely related to most deletions when all cancers were jointly analyzed." (PMID 32488048, 2020). "For example, the fraction of tumors with detectable ESRP1 expression increased from 35.1% in ERG-negative cancers to 42.8% in ERG-positive cancers and with detectable ESRP2 expression from 36.7% in ERG-negative cancers to 51.6% in ERG-positive cancers." (PMID 33339518, 2020). "For the cytoplasmic CD138 expression, significant associations were seen with 6 deletions in all cancers, 4 deletions in ERG positive cancers, and 6 deletions in ERG negative cancers." (PMID 33195694, 2020). "TFAP2D positivity was more common in ERG fusion positive (88.7%) than in ERG negative cancers (66.8%; p < 0.0001)." (PMID 32143573, 2020). "ERG overexpression has a two-fold increase in the chance of developing DTX resistance as compared to ERG-negative cancers in CTCs from CRPC patients treated with DTX." (PMID 35582222, 2020). "It was conspicuous, however, that 8p deletions were strongly linked to membranous and cytoplasmic CD138 positivity in both ERG positive and negative cancers (p < 0.0001 in 3 of 4 analyses)." (PMID 33195694, 2020). "SFRP4 measurement provided independent prognostic information in all scenarios when all cancers were jointly analyzed (p ≤ 0.0027) as well as in the subset of ERG-negative cancers (p ≤ 0.0086)." (PMID 32677026, 2020). "Several other prognostic molecular features exert their prognostic role either in ERG-positive or in ERG-negative cancers." (PMID 33339518, 2020). "(a–c) Impact of cytoplasmic staining (irrespective of nuclear staining) on PSA recurrence-free survival in (a) all cancers, (b) ERG negative cancers and (c) ERG positive cancers." (PMID 32488048, 2020). "The limitation of the prognostic impact of hnRNPA1 to a molecular subgroup such as ERG-negative cancers is not an exception." (PMID 32417965, 2020). "It is not uncommon that the prognostic value of molecular features are limited to ERG positive or ERG negative cancers." (PMID 32143573, 2020). "In primary PCa, this pathway was frequently activated, and separate analysis of TMPRSS2:ERG fusion gene-negative and -positive cancers revealed that the presence of this fusion protein was the most likely cause of Wnt pathway activity." (PMID 30733525, 2019). "An alternative explanation for different prognostic effects between ERG positive and ERG negative cancers is the experimental set-up." (PMID 31043167, 2019). "Nuclear BAP1 expression was associated withTMPRSS2:ERG rearrangement and ERG expression: Strong BAP1 positivity increased from 12-14% in 5,415 ERG-negative cancers (by IHC or FISH) to 30-32% in 4,217 ERG-positive cancers (p<0.0001 each)." (PMID 31903168, 2019). "For our study, we selected deletions that others and us found to be associated with ERG-fusion positive (i.e. PTEN, 3p) or ERG-fusion negative cancers (i.e. 5q, 6q)." (PMID 31452838, 2019). "Matching results (ERG IHC positive and break by FISH) were found in 5,041 of 5,268 (92.2%) cancers." (PMID 31452838, 2019). "It cannot be excluded that our immunohistochemistry protocol was better suited to distinguish expression differences in cancers with generally lower expression levels (ERG negative cancers) than in those with higher expression (ERG positive cancers)." (PMID 31043167, 2019). "Multivariate analyses revealed an independent prognostic impact of high PTPN12 expression in all cancers and in the ERG negative subgroup and to a lesser extent also in ERG positive cancers." (PMID 31606028, 2019).